CD2 (CD2 molecule)
Diseases named in the same sentence as CD2 in open-access papers (continued):
Sharing a sentence is not in itself a finding about the gene and the disease.
Arthritis (4 papers, 2024 to 2026). Inflammation of a joint. "Adoptive transfer resulted in increased arthritis severity at this early time point, highlighting the critical proinflammatory role of CD2+MHC-II+CCR2+ myeloid precursors in an arthritis-conductive environment." (PMID 41482544, 2026). "Collectively these findings suggest that arthritis is controlled not only by the migration of CD2+MHC-II+CCR2+ myeloid precursors from the skin to the joint but also by CD200+ fibroblasts in the joint." (PMID 41482544, 2026). "Our study demonstrated that the development of arthritis depends on the differentiation of CD2+MHC-II+CCR2+ myeloid precursors into highly proinflammatory mononuclear phagocytes." (PMID 41482544, 2026). "Genes commonly associated with T cell activation, such as LAG3, CCL5, ITM2A, CCR5, and CD2, were highly expressed in SF, in comparison to PB T cells of arthritis patients." (PMID 38254179, 2024). "Rather, the local microenvironment, particularly CD200+ fibroblasts, acted as gatekeepers of arthritis, engaging the checkpoint receptor CD200R1 on migrating CD2+MHC-II+CCR2+ myeloid precursors." (PMID 41482544, 2026). "Consistent with our previous observations in mice and humans, we observed an increase in CD2+MHC-II+CCR2+ myeloid precursors and a significant decrease in CD200+ fibroblasts in the synovial tissue during the onset of arthritis in humans." (PMID 41482544, 2026). "After blocking CD200, initially arthritis-resistant animals developed joint inflammation on day 21, supporting the critical gate-keeping role of CD200+ fibroblasts interacting with migrating CD2+MHC-II+CCR2+ myeloid precursors." (PMID 41482544, 2026). "Consequently, intervention with an antibody to CD200 polarized CD2+MHC-II+CCR2+ myeloid precursors toward a proinflammatory phenotype in vitro and allowed the in vivo spreading of psoriatic disease from the skin to the joints even in initially arthritis-resistant mice." (PMID 41482544, 2026).
atherosclerosis (4 papers, 2013 to 2023). A disease characterized by the build-up of fatty material and calcium deposition in the arterial wall resulting in partial or complete occlusion of the arterial lumen. "Up-regulated DEGs of this gene signature included T-cell development, growth and proliferation genes (BATF, CCL5, CD2, EOMES) and F2R, a recognized genetic locus influencing clinical CVD and atherosclerosis development." (PMID 37205656, 2023).
B-cell lymphomas (4 papers, 2013 to 2021). "In the present study, we comprehensively evaluated the expression of T-cell markers (CD2, CD3, CD4, CD5, CD7, and CD8) in 501 B-cell lymphomas, including 225 DLBCLs, by flow cytometry and subsequent immunohistochemistry." (PMID 28380441, 2017). "To this end, we made use of the CD20+ RAJI B cell lymphoma line, which expresses CD58, the ligand of CD2." (PMID 27117418, 2016). "Therefore, the expression of T-cell markers other than CD5, such as CD2, CD4, CD7, and CD8, has not been broadly investigated in a large case series of B-cell lymphomas." (PMID 28380441, 2017).
diffuse large B-cell lymphoma (4 papers, 2016 to 2025). "T-cell markers have been reported to be aberrantly expressed in both small B-cell lymphomas and diffuse large B-cell lymphomas (DLBCL), the most common marker being CD2 in both groups." (PMID 39776705, 2024). "Only very rare cases of diffuse large B-cell lymphoma with aberrant expression of non-CD5 T-cell markers such as CD2 and CD7 have been reported, none of which to our knowledge have CD7 expression while arising in a background of a CD7 negative follicular lymphoma." (PMID 27774324, 2016).
HIV-1 infection (4 papers, 2017 to 2023). The type species of lentivirus and the etiologic agent of acquired immunodeficiency syndrome (AIDS). "We found that CD2 ligation with its cell-free ligand LFA-3 or anti-CD2 antibodies rendered blood resting CD4 T cells highly resistant to HIV-1 infection." (PMID 34765923, 2021). "These previous studies provide a rationale for targeting CD2 to block HIV-1 infection of blood CD4 T cells." (PMID 34765923, 2021). "To examine the longitudinal changes in NK cell subsets with an adaptive signature in HIV-1 infection we compared the expression of Siglec-7, CD2, FcεRI-γ, and PLZF in CD56dim NK cells during early, established infection and post-ART in 5 individuals." (PMID 29616021, 2018). "Our study identifies CD2 as a novel target to block HIV-1 infection of blood resting T cells." (PMID 34765923, 2021). "Furthermore, we directly assessed the proportion of PBMC positive for the HIV-1 antigen p24 and included CD2 in the intracellular stain, as it is a potential marker for latent HIV-1 infection." (PMID 28953327, 2017). "However, we identified a CD4+ T cell population with low levels of intracellular CD2 and high HIV-1 infection rates in comparison to CD4+ CD2+ cells." (PMID 28953327, 2017). "Signaling activation from NKp46, NKG2D, and CD2 crosslinking were not obviously modulated by HIV-1 infection." (PMID 37669308, 2023). "In addition, when CD2 stimulation was performed immediately following HIV-1 infection (CD2 poststimulation), it failed to inhibit HIV latent infection, suggesting that CD2 prestimulation likely triggered a cellular response that selectively blocks viral early infection steps." (PMID 34765923, 2021).
mucositis (4 papers, 2021 to 2025). Mucositis is inflammation and damage of the mucous membranes lining the mouth and other parts of the gastrointestinal (GI) tract. "However, it was also observed that, compared to the placebo group, with the use of L. brevis CD2, fewer patients required analgesics for mucositis-associated pain (p = 0.02)." (PMID 37389790, 2024). "Lactobacillus brevis CD2 lozenges have been shown to reduce the severity and incidence of radio/chemotherapy-induced mucositis in head and neck cancer patients, thereby increasing the likelihood of anticancer treatment completion." (PMID 40003891, 2025).
multiple sclerosis (4 papers, 2015 to 2024). A progressive autoimmune disorder affecting the central nervous system resulting in demyelination. "For example, the acute, benign immune suppression induced by anti-CD2 antibodies in multiple sclerosis has been investigated with a focus on the patients’ T cells." (PMID 33391260, 2020). "Moreover, CD58 and CD2 have attracted attention because of their involvement in various diseases, such as rheumatic arthritis, multiple sclerosis, colorectal cancer, and diffuse large B cell lymphoma." (PMID 29904386, 2018).
Obesity (4 papers, 2013 to 2025). Accumulation of substantial excess body fat. "We found that low parents’ education had a higher risk for both CD2-3 and CD ≥ 4, which mainly resulted from obesity, depressive symptoms, suicide attempts, and school difficulty." (PMID 23962097, 2013).
type-1 diabetes (4 papers, 2015 to 2025). "Investigators using the anti-CD2 biologic Alefacept for treatment of type-1 diabetes have reported promising results." (PMID 33262770, 2020). "For CD2 and CD3, the human genes of S100A9 (calcium binding protein A9) and IGHG1 (immunoglobulin heavy constant gamma 1) have previously identified as genes of interest as is the case with REG1A (pancreatic stone protein) for type-1 diabetes." (PMID 40893175, 2025).
acute leukemia (3 papers, 2019 to 2025). A clonal (malignant) hematopoietic disorder with an acute onset, affecting the bone marrow and the peripheral blood. "There were some aberrant markers which were present in more than one type of acute leukemia such that CD2 was present in B-ALL as well as in AML, CD79a was present in T-ALL as well as in AML and CD13 was present in both B-ALL and T-ALL." (PMID 40103873, 2025). "To evaluate the in vivo antitumor efficacy of CD19-BBζ + CD2 cells, we initially established an acute leukemia model by engrafting 5 × 105 Nalm6 tumor cells overexpressing luciferase (Nalm6-L) one week prior to CAR-T-cell therapy." (PMID 40615696, 2025). "In particular, patient #11944 expressed CD2, CD7 and TdT in 94%, 82% and 26% of cells, respectively, while patient #11945 was also positive for CD3 cytoplasmatic expression, TdT and MPO, with a diagnosis of T/myeloid mixed phenotype acute leukemia (T/M MPAL)." (PMID 31817495, 2019).
acute promyelocytic leukemia (3 papers, 2014 to 2025). An aggressive form of acute myeloid leukemia (AML), characterized by arrest of leukocyte differentiation at the promyelocyte stage, due to a specific chromosomal translocation t(15;17) in myeloid cells. "CD2 was also reported to be highly associated with acute promyelocytic leukemia (APL)." (PMID 33102231, 2020). "CD2+, CD34+, and CD56+ immunophenotypes are associated with poor prognoses of acute promyelocytic leukemia (APL)." (PMID 25045197, 2014). "A single case of Acute Promyelocytic Leukemia (APL, AML-M3) showed CD2 aberrant marker." (PMID 40103873, 2025).
colitis (3 papers, 2016 to 2020). Inflammation of the colon. "More recently, it was shown that treatment of transgenic mice expressing human CD2 in a transfer colitis model with anti-human CD2 mAb CB.219 reduced intestinal inflammation and prolonged survival." (PMID 32582179, 2020). "We have previously demonstrated in a model of DSS-induced colitis that, in contrast to CD2-Tff2 mice, Tff2-null counterparts develop massive splenomegaly by 19–21 days due to the expansion of splenic myeloid CD11b+Gr-1+ cells." (PMID 30042499, 2019). "In contrast to the mild reduction in histologic colitis in CD2–Tff2 transgenic mice in response to DSS treatment, we noted marked reduction in later tumour development in response to AOM/DSS." (PMID 26841680, 2016). "Wild-type mice that received CD2–Tff2 bone marrow suffered the mildest colitis, while recipients of Tff2-null bone marrow had slightly more severe disease (measured by weight loss, spleen size, colonic shortening and colonic IL-1β expression)." (PMID 26841680, 2016). "The importance of T cells as a source of TFF2, as opposed to epithelial gastric cells, was confirmed by bone marrow transplantation of CD2–Tff2, wild-type or Tff2-null donor bone marrow into wild-type mice (5–6 mice per group), followed by the DSS colitis protocol." (PMID 26841680, 2016).
colorectal cancer (3 papers, 2013 to 2024). A primary or metastatic malignant neoplasm that affects the colon or rectum. "On the other hand, we observed an increased level of CD2-associated fluorescence in colorectal carcinomas (IFIS: 8.2 ± 1.5), and this gain was statistically significant with respect to NM and ACF." (PMID 24348178, 2013). "An increase in CD2+ cells was found only in colorectal cancer samples, while the amount of CD2+ cells remained low in ACF." (PMID 24348178, 2013). "We performed an immunofluorescence analysis with anti-CD2 antibody on normal colonic mucosa, ACF, and colorectal cancer." (PMID 24348178, 2013). "Circulating (PB1, PB2, PB3, PB5, and PB6) and intestinal (CD1, CD2, CD3, and NUN) iNKT cells were coincubated with five colorectal cancer cell lines at different effector : target ratios for in vitro cytotoxicity evaluation by measuring lactate dehydrogenase release." (PMID 34535957, 2021).
deafness (3 papers, 2014 to 2025). An inherited or acquired condition characterized by the complete loss of the ability to hear from one or both ears. "The deafness of PCDH15-ΔCD2 mice has been attributed to defects in hair-bundle polarity, a phenotype consistent with Pcdh15-CD2 being an essential component of kinociliary links." (PMID 24940003, 2014).
depression (3 papers, 2021 to 2022). "More importantly, the low PA+CD0 and the low PA+CD2 appeared to be approximately twice the risk of depression than the high PA+CD0 and the high PA+CD2, respectively (p < 0.001)." (PMID 36362583, 2022). "The high PA+CD2 showed a ~6.4-fold increased risk of depression (p < 0.001)." (PMID 36362583, 2022). "In addition, the risk of depression was increased by ~11.9-fold in low PA+CD2 (p < 0.001)." (PMID 36362583, 2022). "In addition, in the CD2 category, the high FRE+DUR30, the high FRE+DUR0, the low FRE+DUR30, and the low FRE+DUR0 showed ~5.5-fold, ~9.3-fold, ~6.2-fold and ~11.1-fold increased risk of depression, respectively (p < 0.001)." (PMID 36362583, 2022).
graft versus host disease (3 papers, 2021 to 2025). An immune system disorder that occurs after allogeneic hematopoietic stem cell transplant and is a reaction of donor immune cells against host tissues. "We recently reported that anti-CD2-decorated nanoparticles (NPs) containing IL-2 prevent a fatal graft versus host disease (GVHD in humanized mice." (PMID 41368646, 2025).
Hodgkins lymphoma (3 papers, 2013 to 2024). A heterogeneous group of malignant lymphoid neoplasms of B-cell origin characterized histologically by the presence of Hodgkin and Reed-Sternberg (HRS) cells in the vast majority of cases. "A review of classic Hodgkin's lymphoma showed that approximately 5% (12 of 259 cases) expressed at least one T-cell marker in the following order: CD2, CD4, CD3, CD5, and CD8." (PMID 23738160, 2013). "Classic Hodgkin lymphoma was ruled out based on the diffuse expression of the T-cell markers CD2, CD3, and CD8, as well as a complete lack of PAX5 expression." (PMID 38921179, 2024).
latent infection (3 papers, 2015 to 2021). "ICAM-1 interaction with leukocyte function-associated antigen (LFA)-1 can facilitate induction of latent infection in the DC-T-cell model, while in other models of in vitro latency CD2 expression, a molecule that binds to LFA-3, was increased on latently infected cells." (PMID 26362311, 2015). "We further tested the effects of prestimulating resting T cells with an anti-CD2 antibody on HIV-1 latent infection." (PMID 34765923, 2021). "The over 90% inhibition of HIV-1 latent infection of resting T cells by CD2 prestimulation, as we observed above, cannot be explained simply by CD2-mediated blockage of viral entry." (PMID 34765923, 2021). "Thus, this CD2-mediated block to HIV latent infection is likely different from known viral barriers in resting T cells." (PMID 34765923, 2021). "Our discovery of the anti-HIV activity of CD2 signaling may offer new therapeutics to prevent HIV latent infection of blood CD4 T cells." (PMID 34765923, 2021). "However, given that CD2 prestimulation led to an opposite, strong inhibition of HIV-1 latent infection, we felt compelled to investigate the effects of CD2 stimulation on cofilin activation in resting CD4 T cells." (PMID 34765923, 2021). "Indeed, our study demonstrated that CD2 prestimulation led to the diminishment of HIV latent infection of resting T cells." (PMID 34765923, 2021). "Therefore, this anti-CD2-antibody-mediated inhibition of HIV-1 latent infection was observed in both X4 (NL4-3) and R5 (AD8) latent infection of resting and resting memory T cells, respectively." (PMID 34765923, 2021). "In addition to triggering cofilin activation and actin polymerization, CD2 stimulation may also induce other cellular factors restricting HIV-1 latent infection of resting T cells." (PMID 34765923, 2021). "Thus, we also tested whether CD2 prestimulation can block latent infection of memory CD4 T cells by R5 virus." (PMID 34765923, 2021). "Given the opposite effects of CXCR4 and CD2 prestimulation on HIV-1 latent infection we speculated that CD2-initiated cofilin and actin polymerization may spatially compete with the HIV-1/CXCR4-initiated cofilin and actin activity that is needed for viral entry and nuclear migration." (PMID 34765923, 2021). "Given the demonstrated ability of CD2 to activate the cofilin pathway, we investigated potential impacts of CD2 signaling on HIV latent infection of resting CD4 T cells." (PMID 34765923, 2021). "In contrast to CD2 signaling, prestimulation of resting CD4 T cells with anti-CXCR4 antibody, with the chemokines CCL19/CCL21, or with IP-10 (CXCL10) has been shown to promote HIV-1 latent infection of resting CD4 T cells." (PMID 34765923, 2021). "However, CD2 stimulation-mediated inhibition of HIV-1 latent infection occurs only before, not after, viral entry." (PMID 34765923, 2021). "Finally, novel small molecule inhibitors of CD2 may need to be developed and tested for inhibiting HIV latent infection of blood CD4 T cells." (PMID 34765923, 2021). "Given that CD2 post-entry stimulation did not inhibit cycles of viral replication, it is unlikely that CD2 stimulation induces unknown restriction factors blocking HIV latent infection." (PMID 34765923, 2021).
lupus (3 papers, 2015 to 2025). "By contrast, the TGF-β producing NK cell we have induced in vivo with CD2 targeted NPs containing IL-2 harvested 5 weeks after NP administration protected lupus mice from renal disease." (PMID 40799646, 2025). "Although the reduction in titers of anti-dsDNA autoantibodies in mice receiving CD2-targeted NPs at weeks 2 and 4 appeared as insufficient to suppress the initial renal damage that develops in lupus BDF1 mice, it resulted in (more evident) beneficial effects after a prolonged time frame." (PMID 33391260, 2020). "Specifically, NPs better protected lupus mice when concomitantly targeted to CD4+ and CD2+ cells, being the suppressive activity on autoantibody production and disease manifestations superior to the sum of the activities deriving from CD4+ and CD8+ Tregs." (PMID 33391260, 2020). "A dose-dependent increase in the frequency of circulating NK cells in BDF1 lupus mice that had received CD2-targeted NPs loaded with IL-2/TGF-β was not seen in non-lupus mice or in mice that had received uncoated NPs." (PMID 33391260, 2020).
mast cell leukemia (3 papers, 2013 to 2025). Mast cell leukemia is a malignant form of systemic mastocytosis (SM) characterized, most of the time, by the presence of circulating mast cells. "In mast-cell leukemia, however, there is often a loss of one or both antigens: a loss of CD25 occurs in 25%, a loss of CD2 in 42%, and 30% of patients are negative for both CD2 and CD25." (PMID 38337573, 2024).
ovarian carcinoma (3 papers, 2021 to 2023). A malignant neoplasm originating from the surface ovarian epithelium. "Low CD2 expression is shown in patients with endometrial or ovarian cancer." (PMID 37963845, 2023). "A recent study showed that CD2 downregulation may attenuate antitumor T cell responses in colorectal, endometrial, and ovarian cancer, and even offset the benefit of PD-1 immunotherapy." (PMID 33968066, 2021).
peripheral T-cell lymphoma (3 papers, 2023 to 2025). "CD2 is a surface adhesion molecule involved in T-cell activation, and while its loss has been described in various peripheral T-cell lymphomas, its absence is less frequently observed in early-stage MF." (PMID 40981343, 2025). "An ultrasound-guided biopsy of an omental implant was performed, revealing large atypical lymphoid cells positive for CD3, CD2, and CD4, and negative for CD5, CD7, and CD8, with a Ki-67 proliferation index of 90%, consistent with an aggressive peripheral T-cell lymphoma." (PMID 40761963, 2025).
Pleural effusion (3 papers, 2012 to 2021). The presence of an excessive amount of fluid in the pleural cavity. "The levels of viral RNA in plasma and CD14+ cells on fever day-2, but not in CD2+ or CD20+ cells, correlated with the size of pleural effusions, an indicator of the severity of plasma leakage." (PMID 23284680, 2012).
Splenomegaly (3 papers, 2012 to 2019). Abnormal increased size of the spleen. "Serial transplantation of 1 500 CD34+CD2+CD7+Lin− cells sorted from a NOTCH1Mutated T-ALL (Patient 05) sample resulted in marked thymic enlargement, splenomegaly and pale marrows indicative of robust leukemic engraftment." (PMID 22768113, 2012). "However, on DSS treatment CD2–Tff2 mice showed insignificant expansion of CD11b+Gr-1+ IMCs, while Tff2-null mice had an exaggerated splenic IMC response with splenomegaly compare with wild-type and CD2–Tff2 mice." (PMID 26841680, 2016).